CST3 (cystatin C)
Diseases named in the same sentence as CST3 in open-access papers (continued):
Sharing a sentence is not in itself a finding about the gene and the disease.
cancer (continued). "Increased levels of cystatin C in tumor tissues have been correlated with a favorable prognosis for cancer patients, whereas higher levels of cystatin C in body fluids have been associated with poor prognosis." (PMID 29088746, 2017). "To test the potential of MpL as a carrier for delivering protein drugs to cancer cells we constructed fusion proteins consisting of MpL and the cysteine peptidase inhibitors cystatin C and clitocypin." (PMID 28460472, 2017). "Cystatin C has also been proposed to have a role allied to the modification of the proteolytic system in cancer." (PMID 28282874, 2017). "Our data are consistent with those from other studies reporting the serum cystatin C levels increase in cancer patients." (PMID 28078200, 2016). "Assessment using serum creatinine and cystatin C concentrations showed changes in renal function among patients with cancer undergoing contrast-enhanced CT examination in this study." (PMID 25961558, 2015). "Cystatin C was shown to play a role in protein catabolism, cancer development, regulation of hormone processing and bone resorption, modulating inflammation." (PMID 23984285, 2013). "Exogenously overexpressed CTSB increased cancer cell invasion and substrate proteolysis, effects that were inhibited by CST3." (PMID 24357805, 2013). "Accordingly, it is ideal for evaluation of the effect of cystatin C on cancer progression via the gene knockout approach." (PMID 21085595, 2010). "Cystatin C expression was significantly lower in cancer specimens than in benign tissues (p<0.001) and there was a statistically significant inverse correlation between expression of cystatin C and MMP2 (rs2 = −0.056, p = 0.05)." (PMID 19956729, 2009). "In the present study, we have shown that in vitro silencing of cystatin C by specific siRNA increased cancer cell invasion in cooperation with Erk2 and AR signalling." (PMID 19956729, 2009). "Abnormal serum levels of cystatin C or cathepsin B/cystatin C complex have been suggested as diagnostics and prognostic indicators for cancers of skin, colon and lung." (PMID 19956729, 2009). "By inactivating cathepsin protease activity, cystatin C inhibits cancer cell invasion and metastasis." (PMID 19956729, 2009). "We provide further evidence supporting a previously proposed role of cystatin C to prevent tumorigenesis and cancer cell invasiveness, possibly due to its ability to inhibit the activity of extracellular matrix proteins." (PMID 19956729, 2009). "Immunohistochemically, cystatin C protein was stained intracellularly in the cytoplasmic compartment of tumour cells in a variety of cancer types." (PMID 15138478, 2004). "The potential benefits of testing cystatin C more widely in patients with cancer is two-fold." (PMID 40973716, 2025). "Intriguingly, elevated cystatin-C levels in tumor tissuescorrelate with a favorable prognosis for cancer patients, while higherlevels in body fluids, and presumably in urine, could be associatedwith poor prognosis." (PMID 41181894, 2025). "The reason for using the combined equation is that cystatin C may be affected by variables such as thyroid disease, corticosteroid use, and cancer." (PMID 40822845, 2025). "Based on a systematic review of the performance of eGFR equations in patients with cancer, the American Society of Onco-Nephrology issued a position statement in 2024 advocating the use of eGFR equations incorporating both creatinine and cystatin C in patients with cancer." (PMID 40973716, 2025). "First, elevated cystatin C expression in cancer patients is the foundation for its oligomerization." (PMID 41233352, 2025). "The less diverse TCR repertoire in individuals with low RTE% could conceivably contribute to the immune escape and development of cancer, while cystatin C and PAI-1 could have an unforeseen role in promoting cancer risk in these patients." (PMID 40591412, 2025).
cancer (continued). "In women, age and presence of other heart disease were most important in both models; the third to seventh most important variables were predicted FEV1 score (%), cystatin-C, number of treatments/medications, number of self-reported non-cancer illnesses, and presence of respiratory disease." (PMID 41267842, 2025). "To date, the tumor-supportive activity of cystatin C could be attributed to the complex functions of cathepsins in cancer and proteolysis-independent mechanisms." (PMID 41233352, 2025). "Second, chemotherapy and radiotherapy may contribute to cystatin C oligomerization during cancer treatment." (PMID 41233352, 2025). "Our findings reveal an unexpected role of oligomeric cystatin C in enhancing myeloid cell immunosuppression, expand the functional spectrum of amyloid proteins and underscore the importance of these proteins in immune evasion and cancer development." (PMID 41233352, 2025). "Cystatin C is proven to be a suitable biomarker to estimate glomerular filtration rate, yet there are some conflicting studies on the reliability of serum cystatin C in cancer patients." (PMID 39365467, 2024). "The results of our MR study including 277,057 participants with no history of cardiovascular events and cancer did not indicate an effect of plasma cystatin C concentration on cardiovascular risk." (PMID 37663661, 2023). "Over the 12-year study period, cystatin C was measured in only 1869 patients with cancer, whereas more than 770 000 patients with cancer had their SCr checked (approximately 0.2% of the population had concurrent eGFRcr and eGFRcys) over the same period (eFigure 1 in Supplement 1)." (PMID 37405775, 2023). "There were 1869 patients with cancer who had a simultaneous SCr and cystatin C measurement between May 2010 and January 2022 (eFigure 1 in Supplement 1)." (PMID 37405775, 2023). "CST3 is known to have various functions on cancer progression, which may be related to the feature that part of PDO155 forms huge clumps." (PMID 36810117, 2023). "In addition, human cystatin C and its analogue in chicken have shown protective effects against cancer cell invasion and parasite infections." (PMID 33837649, 2021). "The present investigation was undertaken to closer examine whether externally added cystatin C has ability to affect cancer cell proliferation and, hence, potential to suppress tumor growth." (PMID 33837649, 2021). "Thus, cystatin C has ability to regulate cancer cell proliferation and, hence, potential to suppress tumor growth." (PMID 33837649, 2021). "Moreover, in a randomized clinical trial on 49 patients with cancer, treatment with cystone and cisplatin caused significant decrease in levels of BUN, serum creatinine, and serum cystatin C compared to treatment with cisplatin alone." (PMID 28975109, 2017). "However, altered expression of cystatin C was reported in different types of cancer, although the levels varied depending on the cancer type." (PMID 29088746, 2017). "However, cystatin C levels have been reported to be altered in some patients with cancer, thyroid dysfunction, or steroid therapy, and smokers." (PMID 27670788, 2016). "In this study evaluating cancer patients undergoing CT with the intravenous injection of low-osmolarity (non-ionic) iodinated contrast, we observed an overall increase in serum creatinine and cystatin C values after contrast administration." (PMID 25961558, 2015). "Decrease of cystatin C in the CSF might contribute to the process of metastasis and spread of the cancer cells in the leptomeningeal tissues." (PMID 23777239, 2013). "CST3, also named cystatin C, was elevated in cancer patients than in controls." (PMID 22830977, 2012). "Nearly 50% of cancers show decreased expression of cystatin C, and perhaps of other cystatins." (PMID 21085595, 2010).
cancer (continued). "The main physiological role of cystatin C is believed to be the regulation of cysteine proteinases secreted from the cells or leaked from the lysosomes during necrotic or apoptotic processes, which links cystatin C with the aetiology of various diseases, including cancer." (PMID 15138478, 2004). "Finally, some researchers reported that cystatin C might be involved in cancer progression by antagonizing the suppressive functions of transforming growth factor β (TGF-β)." (PMID 38665913, 2024). "First, cystatin C was ordered as part of clinical care, which likely selected a population in whom clinicians questioned the accuracy of creatine‐based eGFR; therefore, the rate of eGFR discordance in our study is likely to be higher than in the general cancer population." (PMID 38646842, 2024). "However, in cancer patients, a high tumor cell burden may lead to an increased release of cystatin C into the circulation." (PMID 36143104, 2022). "Indeed, Mendelian Randomization studies have shown that some of our biomarkers (GDF-15, cystatin-C) were not causally associated with cancer and CVD risks, respectively." (PMID 34935094, 2022). "Additionally, some common diseases, for instance cancer and thyroid disease, may also affect serum Cystatin C levels." (PMID 34630276, 2021). "Alternatively, in homogenised preparations used for cystatin C mRNA determination, cystatin C expressing noncancerous stromal cells within tumours with otherwise low expression level of cystatin C in their cancer cells may contribute substantially to the total cystatin C mRNA level." (PMID 15138478, 2004). "Baseline serum cystatin C levels were found to be able to predict recovery of kidney functions in patients with AKI, particularly in subgroups like ICU and cancer patients." (PMID 40707908, 2025). "In combination with creatinine, cystatin C (eGFRcr-cys) improves accuracy of GFR estimation (and therefore dosing accuracy) in the general population as well as populations with cancer." (PMID 40973716, 2025). "In a cross-sectional study including 1611 adults with cancer referred for 1837 determinations of measured GFR (mGFR), we assessed the accuracy of estimated GFR based on creatinine (eGFRcr), cystatin C (eGFRcys) and their combination (eGFRcr-cys)." (PMID 40973716, 2025). "Creatinine-to-cystatin C ratio (CCR) and body composition (BC) parameters have emerged as significant prognostic factors in cancer patients." (PMID 38665913, 2024). "Therefore, the increased expression levels of both Gh1 and Cst3 (as a positive co-expression) and cross talk between the factors, especially via responding to the estradiol pathway, may play a key role in the progression of cancer." (PMID 35180880, 2022). "When cancer-specific survival (CSS) was predicted, the HR for high levels of cystatin C was 4.944 (P = 0.048)." (PMID 36589819, 2022). "The deregulated proteins found in the pools of cancer vs. control serum samples—PEDF, IGKC, CD44, and CST3—have been previously reported." (PMID 33224883, 2020). "Serum creatinine, serum cystatin C concentrations, and GFR were determined simultaneously in 52 cancer patients received carboplatin-based or cisplatin-based chemotherapy." (PMID 28078200, 2016). "The vast majority of studies have evaluated the role of cathepsin B (CTSB) and its inhibitor cystatin C (CYST C) in cellular growth and angiogenesis in cancer diseases." (PMID 26904684, 2016). "Serum cystatin C correlates well with measured GFR and more accurately measures kidney function than does serum creatinine in the elderly, cancer patients, diabetics, and renal transplant recipients." (PMID 18414901, 2008). "We identified the cysteine protease inhibitor cystatin C (CystC) as a novel TGF-β type II receptor antagonist that inhibits TGF-β binding and signaling in normal and cancer cells." (PMID 16168131, 2005).
cancer (continued). "Various participant and cancer characteristics may impact the accuracy of GFR estimates using creatinine and cystatin C. Creatinine is primarily impacted by muscle mass and function." (PMID 40973716, 2025). "We demonstrated that oligomeric cystatin C enhances the immunosuppressive activity of myeloid cells by engaging LILRB2/5 inhibitory receptors, thereby suppressing T-cell function and promoting cancer progression." (PMID 41233352, 2025). "Among 474 possible TAVI candidates, we excluded 8 patients who died in the hospital and 31 patients with active cancer and 45 patients without serum cystatin C data at the time of discharge." (PMID 37187794, 2023). "After reviewing the literatures on cytokine functions, we determined two candidates as fibroblast-inhibiting cytokines: cystatin C (CST3) has been reported to inhibit fibrosis by antagonizing TGF-β;22,23 growth differentiation factor 15 (GDF15) to induce cancer cell death." (PMID 29724997, 2018). "An increase in phosphorylated p-38 was observed in CstC knockout tumors, suggesting a novel function for cystatin C in cancer development, independent of the TGF-β pathway." (PMID 29088746, 2017). "Further work is necessary to investigate whether cells actively modulate the amount of secreted cystatin C to compete with extracellular cathepsins available to degrade ECM and assist cancer cell invasion." (PMID 26349896, 2015). "Therefore, the aim of the study was to assess the agreement between Cr and cystatin-C (CysC) based GFR estimation equations and GFR estimated by Cockcroft-Gault for appropriate chemotherapy dosing in cancer patients undergoing assessment for first-Line chemotherapy at an oncology unit of St." (PMID 40504791, 2025). "Moreover, CST3 expression was significantly positively correlated with the expression of LILRB2 or LILRB5, particularly LILRB2, in most of these cancer types, although these observed Spearman’s rho values were within the range typically considered weak correlations." (PMID 41233352, 2025). "Of note, most studies evaluating the non-GFR determinants of cystatin C did not include patients with cancer, and the incidence of factors such as thyroid dysfunction and corticosteroid exposure in patients with cancer is not well known and likely varies throughout cancer treatment." (PMID 39992722, 2025). "The findings are in keeping with those seen in general population settings, despite concerns that the non-GFR determinants of creatinine and cystatin C may be augmented among people with cancer." (PMID 40973716, 2025). "A recent study showed that the creatinine/cystatin C ratio was significantly correlated with CT and BIA in assessing muscle mass, and could be conveniently used as a reliable biomarker for muscle in patients with cancer." (PMID 37409249, 2023). "However, several indicators, including the number of bone metastases and cystatin C levels, did not reveal any further relationship with the progression of cancer." (PMID 36589819, 2022). "When adjusted for age, cancer history, lymphocyte, neutrophil, and platelet counts, lactate dehydrogenase level, serum creatinine, and corticosteroid treatment, elevated cystatin C levels did not have significantly greater risks for death (HR: 1.366, 95% CI: 0.292–6.402, and p = 0.692)." (PMID 33828483, 2021). "However, in some cancer patients, the serum cystatin C is not appropriate for estimating GFR because of its production by cancer cells." (PMID 33024521, 2020). "Different investigators stated that the level of cystatin C is influenced by the extent of the tumor, however, they were not able to find out if the significant correlation between cystatin C levels in sera and tumor burden is reliant on the primary site of the cancer." (PMID 28282874, 2017).
cancer (continued). "Our aim was to assess renal function using as laboratory measurements serum creatinine and cystatin C concentrations before and after administration of low-osmolarity (nonionic) iodinated contrast medium in patients with cancer undergoing computed tomography (CT)." (PMID 25961558, 2015). "In the KDIGO guidelines, patients with cancer are noted as a population in which non-GFR determinants of both creatinine and cystatin C may be more profound, requiring a better understanding of these elements." (PMID 39992722, 2025). "Thus, investigations with cystatin C for cancer and non-CVD/non-cancer mortality are warranted." (PMID 27092943, 2016).